CD34 (CD34 molecule)
Diseases named in the same sentence as CD34 in open-access papers (continued):
Sharing a sentence is not in itself a finding about the gene and the disease.
tumor (continued). "Stroma between tumor cell clusters stained with CD31 and CD34 suggesting an induction of angiogenesis." (PMID 28475639, 2017). "Ex vivo histologic examination of the tumor grafts by H&E showed increased vascularity as well as increased P4HB, CD31 and CD34 staining in P4HB over-expressing cells." (PMID 29069756, 2017). "Syndecan-1 (CD138), MUC-1 (CD227) CD45, CD34, and the putative cancer stem cell markers CD15, CD24, CD44, and CD133 surface expression were evaluated on CSF floating tumor cells." (PMID 28399903, 2017). "On immunohistochemical examination, the tumor cells were positive for alpha-smooth muscle actin (SMA), desmin, CD34, and h-caldesmon, and CD99 was weakly and focally expressed." (PMID 28214470, 2017). "After exclusion of suboptimal/inadequate cores from the stained TMA sections a total of 164 cases had both CD34+ and VEGFR2+ tumor stromal vessel counts from the same TMA cores for comparison." (PMID 28533703, 2017). "Consistent with our previous work with hDLL4, mDLL4 significantly diminished CAIX expression in mDLL4-tumours compared to that in EV-tumours as revealed by CAIX (brown) and CD34 (grey) dual staining and by its quantification." (PMID 28445154, 2017). "Then the transfected SaOS-2 cells were inoculated in nude mice and transplantation tumor were checked via HE staining, VEGF and CD34 immunohistochemistry, and calculation of microvascular density (MVD)." (PMID 28523034, 2017). "The co-localization of CD34 and AmotL2, FKBP51 and IQGAP1 in several vessels is indicative of a role for these three scaffoldings in tumor angiogenesis and/or in vascular invasion." (PMID 28441737, 2017). "The immunohistochemical study showed overlap staining of CD34 and PSMA staining in the neo-vasculature of tumor." (PMID 29088775, 2017). "We also compared our Tgfbr2 cKO anorectal SCC CD34+ CSC gene signature with DMBA-induced skin SCC CD34+ cells with overexpression of VEGF, which accelerates tumor growth." (PMID 28219480, 2017). "Meanwhile, we estimated tumor angiogenesis by detecting VEGFA, ESM-1 (endothelial cell specific molecule 1), and CD34 levels by ELISA assays." (PMID 28178668, 2017). "While Bulun’s group have reported CD34+/CD49+ cells in myometrial SP which also express KLF4, NANOG, SOX2 and OCT-4 as the possible myometrial stem cells and also tumor initiating cells." (PMID 28438190, 2017). "The immunoprofile of the tumor was as follows: CD117 >50%: 3 (+), CD34 >50%: 1 (+), smooth muscle actin (SMA) <10% 1 (+), S-100 (-), desmin (-), Ki67 1%." (PMID 28418346, 2017). "IHC staining showed that CD34 was expressed mainly in the epithelial cells of microvessels, whereas VEGF-A, PDGF-B and bFGF were expressed mainly in the cytoplasm of tumour cells." (PMID 28515673, 2017). "The microvascular density (MVD) in the largest tumor of each mouse was characterized by immunohistochemical (IHC) staining using CD31, CD34 and CD105 antibodies that specifically recognize endothelial cells." (PMID 29088837, 2017). "Staining for CK7 revealed incorporation of alveolar walls into the metastases, and co‐staining for CD34 and CK7 highlighted that these tumours incorporate pre‐existing alveolar capillaries." (PMID 27859259, 2017). "Routine IHC analysis of this tumor showed positive staining of endothelial markers CD31, CD34, smooth muscle marker Calponin, and mesenchymal cell marker vimentin." (PMID 29113426, 2017). "While there was significantly lower expression of CD34 in MEC and MES normal and tumor primary cell lines compared to blood cells, interestingly, ADSC CD34 expression was in general significantly greater among primary cell lines." (PMID 26968831, 2016). "To determine the potential in vivo role of 11βHSD1 in tumor angiogenesis, we determined the expression of CD31 and CD34 by IHC in subcutaneous tumors derived from 7721-vector and 7721-HSD11B1 cells." (PMID 26700460, 2016).
tumor (continued). "Immunohistochemical evaluation of MVD using antibodies against CD34, CD31, and CD105 has been performed to evaluate tumor angiogenesis." (PMID 27982164, 2016). "According to the changes observed in the vasculature, we completed the study with the expression analysis of endothelial-related genes in tumor lysates, such as CD31 (PECAM1), CD34, and VEGFR2 (KDR)." (PMID 27120788, 2016). "Pathological examination revealed that the tumor was composed of viable spindle cells with 15 mitoses/50 HPF that stained positively for CD117 (KIT) and CD34." (PMID 27864817, 2016). "On Immunohistochemical staining, the tumor cells were positive for CD32, CD34, Vimentin and smooth muscle actin." (PMID 26739818, 2016). "Tumour volume, apoptosis (TUNEL, Caspase 3), proliferation (Ki67) and angiogenesis (CD34, VEGF and endothelin) were analysed." (PMID 27765923, 2016). "To explore the mechanism underlying tumor regression, we sacrificed a second set of identically treated mice on the 10th day after treatment began, and tumor tissues were embedded and stained with HE, Ki67, TUNEL, and CD34." (PMID 27825114, 2016). "The tumor cells reacted with immunohistochemical stains for desmin, smooth muscle actin, SMMHC, CD34 (focal), and vimentin." (PMID 27747117, 2016). "Immunohistochemically, tumor cells demonstrated diffuse positive staining with vimentin, CD31, CD34, and D2-40 favoring their vascular origin." (PMID 27747121, 2016). "We found that the growth of the tumor xenografts was significantly inhibited by wortmannin, while immunohistochemical staining showed HIF-1a and CD34 expression was significantly decreased." (PMID 27456341, 2016). "pSTAT3 staining (red) was localized to cells within the tumor nests that displayed membranous staining for EMA (green), the endothelium of the microvessels that stained positively for CD34 (green) and cells within the stroma." (PMID 27532037, 2016). "All patients had records of primary tumor sites, tumor sizes and mitosis, however, CD117, DOG-1, and CD34 expressions were collected from 139, 93, and 132 patients, respectively." (PMID 26848617, 2016). "As angiogenesis is the requirement for tumor metastasis, we detected the effect of PLCγ1 shRNA on the two biomarkers of angiogenesis, VEGF and CD34." (PMID 26811493, 2016). "Data from hierarchical cluster analysis for all patients suggested the following stratified cluster analysis based on sex, age, tumor sites, tumor sizes, mitosis, CD117, DOG-1, and CD34 expression." (PMID 26848617, 2016). "The tumor stained positively for CD117 (KIT) and CD34, and it was composed of spindle cells with >5 mitoses/50 high-power fields (HPF)." (PMID 27864817, 2016). "We found that the growth of the NSCLC tumor xenografts was inhibited by PD98095, while immunohistochemical staining showed that HIF-1a and CD34 expression was significantly decreased." (PMID 27456341, 2016). "Tissue analysis for our patient showed the tumor cells stained positive for CD31, CD34, CD68, S-100, vWF, and Ki-67." (PMID 27651973, 2016). "It is concluded that use of immunostaining of cellular antigens like Vimentin, S100, EMA, CEA, GCDFP 15, CD10, p63, CD34, pan-cytokeratin (AE1/AE3), CK5, CK6, and CK7 is helpful in diagnosing such tumours." (PMID 27034895, 2016). "SFT cells are positive for CD34 in 90–95% of tumours, MIC2 in 70% of tumours and Bcl-2 in >80% of tumors." (PMID 25663869, 2015). "In aid to differential diagnosis, the immunochemistry is very useful because the tumour cells of AMF express desmin and rarely CD34 and smooth muscle actin." (PMID 26187500, 2015). "The tumour typically stains positive with endothelial markers CD31 and CD34 and factor VIII-related protein." (PMID 26435872, 2015).
tumor (continued). "The same authors showed that CD34+ cells (mostly tumor cells) of CML patients expressed MDSC markers; however, MDSCs were identified on both CD34- and CD34+ cell populations." (PMID 26029664, 2015). "It was recently demonstrated that it is possible to expand activated, tumor cytotoxic and pure NK cells by differentiating UCB CD34+ HSC under cGMP condition." (PMID 26648934, 2015). "In the nude mice tumor model, we detected the cancer tissue expressions of CDK11p58, VEGF, CD31 and CD34 by IHC." (PMID 26470709, 2015). "We further showed the immunohistochemical staining results of Ki67, CD34, p-VEGFR2 and p-STAT3, on tumor sections." (PMID 25789853, 2015). "One of the potential sources to accomplish clinically relevant doses of tumor-reactive NK cells is making use of HSC (CD34+) through differentiation and expansion of CD34+ cells isolated from bone marrow, peripheral blood, or UCB into functional NK cells." (PMID 26648934, 2015). "In our study, in TJ905 stem cell group the CD34 expression was much higher than that in TJ905 cell group, which also shows the transplanted tumor that originates from cancer stem-like cell has a stronger malignance." (PMID 26136642, 2015). "Immunohistochemically, tumor cells were diffusely positive for vimentin and CD99, focal positive for CD34, bcl-2 and Actin." (PMID 26155787, 2015). "Immunohistochemical examination revealed the presence of numerous tumor markers, including CD99+, Bcl-2+, partial CD34+, focal S-100+, SMA+ and CD68−." (PMID 25452776, 2015). "On immunohistochemistry very sparse tumor cells expressed smooth-muscle-actin (mainly lining directly vascular spaces), CD31 and CD34." (PMID 26351605, 2015). "Isolated tumor tissues were CD31- and CD34-positive with an irregular staining distribution on the cell membrane; furthermore, tumor tissues exhibiting vascular and pseudovascular structures were always stained positive for CD31 and CD34." (PMID 24959280, 2014). "Immunohistochemical staining of CD31, CD34 and VEGF was carried out to detect the tumor vascularity." (PMID 24901647, 2014). "The expression density of CD34 on repair blastema ECs was similar to that found on heart or lung ECs, whereas the expression density of CD102 was more similar to that seen in tumor ECs." (PMID 24632811, 2014). "Immunohistochemical studies showed that the tumor cells were diffusely positive for CD34 and CD 31, the stroma cells were positive for SMA, and Ki-67 showed low proliferation activity of the tumor cells." (PMID 25102914, 2014). "The tumor cells were positive for tumor cell glial fibrillary acidic protein (GFAP), S-100 protein, vimentin, human leukocyte differentiation antigen 34 (CD34), epithelial membrane antigen (EMA), cluster of differentiation 99 (CD99) and D2-40." (PMID 24348765, 2014). "Ninety-five percent of the RETAAD tumor cells were CD34− CD271− (hereafter denoted as CD34−), while the CD34 and CD271 single positive populations accounted for less than one percent." (PMID 25294815, 2014). "Immunohistochemical analysis of the tumor cells revealed focal positivity for c-KIT and SMA, and negativity for CD34 and S-100." (PMID 25037940, 2014). "Cytologically, the tumor cells were generally bland and exhibited positivity for CD31 and CD34 immunohistochemically." (PMID 25102914, 2014). "Similar to the primary tumor, lung metastases of DNIIR tumors have also increased vessel presence as observed in CD34 staining." (PMID 25280532, 2014). "Both CD34-positive and tomato lectin-positive blood vessel densities in SAS-R tumor tissues decreased remarkably after the Everolimus and radiation treatment." (PMID 24464839, 2014). "To confirm our immuno-histochemical analysis of CD44, CD24, CD34, CD117 and Oct4 positive cells in orthotopic tumors, we performed Western blot analysis of the tumor extracts using specific antibody for markers detected by immuno-histochemical staining." (PMID 25264898, 2014).
tumor (continued). "To further characterize what conditions tumor were sensitive and resistant to anti-angiogenesis therapies, we compared the expressions of VEGF, CD34, and DLL4 density in the two groups." (PMID 24931473, 2014). "The tumor cells diffusely and strongly expressed CD117, CD34 and DOG1; therefore, the prostate was considered to be the origin of the tumor." (PMID 24932260, 2014). "Primary ECs directly after isolation from heart, lung, repair blastema and tumor were characterized by flow cytometric analysis using EC-specific antibodies directed against CD31, CD105, CD144, CD34, CD54 and CD102." (PMID 24632811, 2014). "The present study provides evidence that BM-derived EPCs, defined by the cell surface expression of CD34 and CD133, differentiate into mature endothelial cells and contribute structurally and functionally to tumor neovascularization." (PMID 24765203, 2014). "Expression of CD31, CD34 and VEGF also proved that the combination of resveratrol and As2O3 suppressed the microvascular of xenograft tumor." (PMID 24901647, 2014). "Tumour sections were immunostained with a primary anti-tryptase antibody (clone AA1; Dako, Glostrup, Denmark) and an anti CD-34 antibody (QB-END 10; Bio-Optica Milan, Italy) by means of immunohistochemistry and then evaluated by image analysis methods." (PMID 24915568, 2014). "Some tumour cells were positive for CD117 (c-kit), whereas all of them were negatively stained for CK7, CK20, Desmin, and CD34." (PMID 24587922, 2014). "DTCs were detected using immunocytochemistry, the level of tumor hypoxia using NMR spectroscopy, CD68, CD34, VEGF, and VEGFR-1 (Flt-1) expression using immunohistochemistry, and MMP-2 and MMP-9 activity using zymography." (PMID 24669218, 2014). "To investigate the tumor vasculature, we carried out immunofluorescence by confocal microscopy using the endothelial antigens vWF, CD31, and CD34 as markers." (PMID 24722469, 2014). "The immunohistochemical profile was consistent with the one described in AT in usual locations (genital tracts) and was typical for a tumor of mesothelial origin: calretinin (+), CK(cytokeratin) 5/6 (+), CK 7(+), vimentin (+), D2-40 (+), CD31(-) and CD34 (-)." (PMID 25487416, 2014). "In contrast a significant increase in expression of CD24, CD34, CD44 and Oct4 was observed in tumor extracts from animals treated with CIS (6 mg/kg) as compared to mock-treated mice or mice treated with WFA (2 mg/kg) alone." (PMID 25264898, 2014). "CD34 and collagen IV co-staining of xenograft tissue sections and human HCC tissue sections demonstrated that tumor vessel walls in the EIF5A2 low expression group were more smooth and continuous." (PMID 25071013, 2014). "The results demonstrated that HIF-1α, VEGF and CD34 were overexpressed in the 22 sacral GCTB specimens, and overexpression of HIF-1α and VEGF correlated with the tumor MVD." (PMID 25289039, 2014). "Immunostaining showed that the tumor was positive for the Vimentin, Desmin and MyoD1, and was negative for CK, P63, NSE, CD45, CD30, S-100, CD99, Myoglobin, CD68, CD34, CD31, and α–SMA." (PMID 23379991, 2013). "Immunohistochemically, the tumor cells are reported to be positive for Von-Willebrand factor, CD31, CD34, and vascular endothelial growth factor receptor-3 (VEGFR-3)." (PMID 23607024, 2013). "Immunohistochemical analysis revealed that the tumor cells were positive for the endothelial markers, factor-VIII-related antigen and CD34." (PMID 23759830, 2013). "The tumor was diffusely positive for CD31, CD34, and ERG, with SMA-positive smooth muscle seen focally around vessel walls, and negative for AE1/AE3, S100 protein, desmin, and HHV8." (PMID 24383023, 2013). "Other intestinal spindle cell tumors typically express positivity for CD34 and CD117, as well as tumor-specific markers." (PMID 24137370, 2013).
tumor (continued). "The discrepancies in the prognostic significance of MVD can, in part be explained by considering several factors: tumor heterogeneity, pan-endothelial marker utilised (anti-CD31; anti-CD34; anti-FVIII-RA) and the variability in the choice of hot spots." (PMID 23326384, 2013). "Immunohistochemical analysis showed that the tumor cells were positive for cytokeratin (CK), CAM5.2, smooth muscle actin (SMA), CK19, calretinin (CR) and CD34." (PMID 23946800, 2013). "Tumor tissue samples were characterized by histopathology and immunohistochemistry for Glut1, FASN, Ki67, and CD34." (PMID 22875335, 2013). "The tumor cells in the present case were positive for CK, CAM5.2, SMA, CK19, CR and CD34, while the markers for bcl-2, PLAP, CD117, S-100, CD20, CD79a, CD45RO, CD15, CD30 were negative." (PMID 23946800, 2013). "By immunohistochemistry, the tumor cells were positive for CD31, CD34 and D2-40 at varying intensity." (PMID 24063649, 2013). "Immunostaining showed that the tumor was strongly positive for Vimentin, Desmin and MyoD1, and was negative for CK, P63, NSE, CD45, CD30, S-100, CD99, Myoglobin, CD68, CD34, CD31, α–SMA." (PMID 23379991, 2013). "In our own current practice, we carry out double-labelling for MGMT and "cocktail" (CD34, CD45 and CD68) to come to an initial conclusion as to the likely methylation status of the tumour." (PMID 24252243, 2013). "In the present case, the large size, presence of necrosis and positive expression of CD117, CD34 and PDGFRA in the tumor cells suggested a malignant potential, while the low mitotic rate (<10/50 HPF) did not favor this conclusion." (PMID 24137442, 2013). "The tumor showed diffuse and strong positivity for CD31, CD34, FLI1, and INI1, with smooth muscle actin (SMA) positive surrounding smooth muscle layers around most vessels." (PMID 24383023, 2013). "In this case, tumor cells showed diffuse and strong positivity for CD117 (KIT) and CD34, which was consistent with a diagnosis of GIST." (PMID 22988538, 2012). "Tumor cells, especially myomatous cells, were stained positive for HMB-45 in most tumors, for CD34 in the endothelial cells of the blood vessels and for smooth muscle actin in spindle smooth muscle cells." (PMID 23320180, 2012). "In-vivo efficacy of adenoviral delivery of the human MDA-7 gene was assessed in nude mice bearing HepG2 cell lines in vivo by determining inhibition of tumor growth, VEGF and CD34 expression, and microvascular density (MVD)." (PMID 23554730, 2012). "As a possible mechanistic explanation for AdvGFP/MDA-7-induced reduction in tumor growth, the ability of AdvGFP/MDA-7 to alter the expression of VEGF and CD34 in tumors was assessed." (PMID 23554730, 2012). "The number of apoptotic cells and microvascular density (MVD) in tumor tissues were assessed by TUNEL and CD34 immunostaining." (PMID 22916270, 2012). "GISTs typically express c-kit, CD34, the smooth muscle antigen (SMA) and S100, but the expression of these factors vary according to the localisation of the tumour." (PMID 22826743, 2012). "Immunohistochemically, expression of CD31, CD34, and FLI-1 is the most reliable feature for diagnosis of this tumor." (PMID 23133773, 2012). "As many as 90-100% of tumour cells exhibited strong immunopositivity for CD117, DOG-1, and CD34 and were generally immunonegative for SMA and S-100." (PMID 23111239, 2012).